JARID2 (jumonji and AT-rich interaction domain containing 2)
Diseases named in the same sentence as JARID2 in open-access papers (continued):
Sharing a sentence is not in itself a finding about the gene and the disease.
periodontitis (1 paper, 2025). An acute or chronic inflammatory process that affects the tissues that surround and support the teeth. "Jarid2 and Mtf2, involved in chromatin remodeling and gene repression, contribute to the persistent inflammatory environment and tissue destruction observed in the advanced stages of RA and periodontitis." (PMID 40076622, 2025).
preeclampsia (1 paper, 2024). Preeclampsia is a hypertensive disorder of pregnancy that is characterized by new-onset hypertension with proteinuria presenting after 20 weeks of gestation, and depending on mild or severe forms may initially present with severe headache, visual disturbances, and hyperreflexia. "Additionally, the potential therapeutic significance of JARID2 in addressing Preeclampsia has been proposed." (PMID 38628314, 2024).
Primary microcephaly (1 paper, 2020). Head circumference below 2 standard deviations below the mean for age and gender at birth. "In a patient (M-001) with primary microcephaly, we found a de novo variant (c.2123A>C;p.Tyr708Ser) in the JARID2 gene." (PMID 33584783, 2020).
sarcoma (1 paper, 2021). A usually aggressive malignant neoplasm of the soft tissue or bone. "Among the seven survival-associated mRNAs, the high expression levels of SMARCC1, SRSF10, PRPF38A, JARID2 and GNAI3 were significantly associated with shorter overall survival in sarcomas (P = 0.0018, P = 0.037, P = 0.0058, P = 0.0093, and P = 0.0234, respectively)." (PMID 33653335, 2021). "Among them, high expression levels of SMARCC1, SRSF10, PRPF38A, JARID2, GNAI3, miR-301a-3p, miR-106b-5p, miRNA-130b-3p, miR-423-3p and LINC01296 and low expression levels of ARF3 and PRKCB were associated with shorter overall survival in sarcomas." (PMID 33653335, 2021).
seminoma (1 paper, 2015). A radiosensitive malignant germ cell tumor found in the testis (especially undescended), and extragonadal sites (anterior mediastinum and pineal gland). "From them, EC-, pluripotency- and reprogramming-associated genes REX1 (ZFP42), DND1, JARID2 and PRDM14 were hypomethylated and upregulated, while seminoma-related genes PRDM1, PROM1 and IGF1 became hypermethylated and were downregulated." (PMID 26226633, 2015).
skin cutaneous melanoma (1 paper, 2018). "Interestingly, both the genes queried were highly ranked and showed opposite Cox coefficient signs, positive for JARID2 and negative for SFRP1, in several cancer types including skin cutaneous melanoma (SKCM) and breast invasive carcinoma (BRCA)." (PMID 30119689, 2018).
vitamin D deficiency (1 paper, 2023). A nutritional condition produced by a deficiency of VITAMIN D in the diet, insufficient production of vitamin D in the skin, inadequate absorption of vitamin D from the diet, or abnormal conversion of vitamin D to its bioactive metabolites. "Vitamin D deficiency epigenetically suppresses Jarid2 expression and activates the Mef2/PGC1a pathway in HSCs, which persists in recipient bone marrow, resulting in adipose macrophage infiltration." (PMID 37311757, 2023). "Together, these data identify that the Jarid2/Mef2/PGC1α program induced by vitamin D deficiency in utero enables the communication between innate immune cells, adipocytes, and JG cells to cause cardiometabolic disease." (PMID 37311757, 2023). "In our study, we found that vitamin D deficiency in utero persistently downregulates Jarid2 expression and activates the immune cell Mef2/PGC1α pathway in donor HSCs, recipient BM, and adipose macrophages despite postnatal VD supplementation, suggesting a stable epigenetic program in immune cells." (PMID 37311757, 2023). "In this study, NGS confirmed that vitamin D deficiency promotes methylation of numerous CpG islands in putative enhancers of intron one between the two promoters of the mouse Jarid2 gene in recipient BM, and importantly this methylation is conserved at six months in recipient adipose macrophages." (PMID 37311757, 2023).
tumor (29 papers, 2012 to 2025). "NGS has also indicated a JARID2 mutation (a gene involved in metastasis) and a high tumor burden (TMB) as markers of poor TNBC outcomes." (PMID 37298642, 2023). "In the case of JARID2, a previous report showed a strong association of JARID2 gene deletion with leukemic transformation of chronic myeloid malignancies, confirming tumor-suppressive function of PRC2 members in these cell lineages." (PMID 25542019, 2014). "This demonstrated a highly complex tumor immune microenvironment associated with JARID2." (PMID 38961353, 2024). "Future research should further study the complex interactions between different members within the chromatin structural domain of the PRC2 gene and explore the connection between JARID2 and the tumor immune microenvironment." (PMID 38961353, 2024). "Considering the diverse roles of immune cells in tumor progression, the immune-related functions of JARID2 still need more exploration." (PMID 38961353, 2024). "Previously, EZH2, SUZ12, EED, MTF2 and JARID2 have all been suggested to not only act as oncogenes, but also to have tumor suppressor activities, depending on the type of cancer." (PMID 38562687, 2024). "Initially, we examined data from the TCGA database to establish that the expression of JARID2 was elevated in tumor samples compared to normal samples or adjacent normal samples from patients with OSCC." (PMID 38961353, 2024). "Overexpression of JARID2 promoted the viability, invasion, and migration of OSCC cells, and it was closely associated with tumor immune microenvironment and drug sensitivity." (PMID 38961353, 2024). "The relationship between the expression of the JARID2 gene in tumor samples of OSCC patients and clinical pathological factors was analyzed using immunohistochemistry experiments and RT-qPCR analysis." (PMID 38961353, 2024). "Further studies are needed to define ANGPTL2‐mediated transcriptional regulatory mechanisms of JARID2 in tumor cells." (PMID 37452654, 2023). "JARID2 has been reported to facilitate tumorigenesis and epithelial-mesenchymal transition in bladder cancer and acts as a tumour suppressor in myeloid neoplasms." (PMID 35127746, 2021). "The expressions of ARID1A, ARID2, ARID3C, JARID1C and JARID2 were strongly correlated with tumour stage." (PMID 35127746, 2021). "Instead, Jarid2−/− cells were less effective than their wild-type counterpart at controlling tumor growth and extending mice survival." (PMID 31089138, 2019). "To further evaluate the contribution of Jarid2 in CD8+ T cell antitumor immunity we transferred pmel-1 Jarid2−/− CD8+ T cells into tumor-bearing mice in conjunction with gp100-VV and interleukin-2 (IL-2) administration." (PMID 31089138, 2019). "The results showed that, compared with matched adjacent non-tumor liver tissues (ANLTs), the expression level of JARID2 in HCC tissues (T) was significantly up-regulated (fold change (T/ANLT) > 2) in 73.3% cases (22/30)." (PMID 27259236, 2016). "In training cohort, high JARID2 expression in HCC tissues positively correlated with tumor number (P = 0.002), microvascular invasion (P = 0.001), Edmondson-Steiner grade (P = 0.004), HCC subtype (P = 0.007), TNM stage (P = 0.042) and BCLC stage (P = 0.049)." (PMID 27259236, 2016). "In this study, the data indicated that JARID2 was highly expressed in HCC tissues relative to the adjacent non-tumor liver tissues (ANLTs), which correlated with HCC metastasis and predicted poor prognosis of HCC patients." (PMID 27259236, 2016). "Data showed that high JARID2 expression in HCC tissues also positively correlated with tumor number (P < 0.001), microvascular invasion (P = 0.004), Edmondson-Steiner grade (P = 0.002), HCC subtype (P = 0.001), TNM stage (P = 0.005) and BCLC stage (P = 0.006)." (PMID 27259236, 2016). "This study found that JARID2 expression was significantly higher in HCC tissues than that in adjacent non-tumor liver tissues (ANLTs), and its expression level correlated with HCC metastasis." (PMID 27259236, 2016).
tumor (continued). "Jarid2 plays an important role during embryonic development and cell differentiation, functions as a tumor suppressor in hematological disorders, and was shown to suppress cell proliferation as well as to negatively influence B-cell survival." (PMID 23185331, 2012). "Tumor formation and growth were suppressed in JARID2 KD U251-bearing mice." (PMID 40288646, 2025). "While JARID2 may have a tumor-suppressive role in FP-RMS, its impact on the epigenome of recipient cells and subsequent functional changes in RMS is unclear." (PMID 38730605, 2024). "Study of clinical samples from patients suggests that JARID2 may closely influence tumor staging and indicate a potential indicator of poor prognosis." (PMID 38961353, 2024). "The mRNA expression of ARID3A, ARID3B, ARID4B, JARID1B, JARID1C, JARID2 in tumor tissues was more expressive in normal tissues, ARID1B, ARID3C, ARID4A, ARID5A, ARID5B, JARID1A mRNA expression in tumor tissues were lower than that in the normal tissues (p<0.05)." (PMID 33592583, 2021). "The PRC2 complex is composed of several subunits (EZH2, EED, SUZ12, JARID2 and Rbap46.48), which are often amplified in MB, and their actions leads to an elevated level of H3K27me3 by repressing specific tumor suppressor genes, thus facilitating tumor development." (PMID 36968588, 2023). "However, it remains unclear how the ANGPTL2‐α5β1 integrin pathway regulates JARID2 expression in tumor cells." (PMID 37452654, 2023). "Interestingly, a number of recent reports suggest that Jarid2 may act as a tumor suppressor in hematopoietic malignancies, a function which would be compatible with its negative influence on cell growth and cell survival." (PMID 23185331, 2012). "Therefore, these pathways may regulate JARID2 expression in tumor cells." (PMID 37452654, 2023). "Although slightly higher expression levels were observed in tumor samples, the expression levels of these transcripts were much lower than EZH2/JARID2 specifically bound genes in HepG2 cells." (PMID 36578923, 2022). "Based on this rationale, four potential genes (JARID2, FRK, DR5 and TGFBR3) were selected from the databases of miRwalk, miRanda and TargetScan according to their potential functions in tumor suppressive processes." (PMID 27129166, 2016). "Notably, the knockdown of JARID2 significantly reduced GBM stemness, suppressed tumor growth, and extended the survival of xenograft mice." (PMID 40288646, 2025). "Similarly, the infiltrations of both anti-tumor immune cells (CD56dim natural killer cell) and tumor-promoting immune cells (monocyte, activated CD8 T cell) were observed to be negatively correlated with JARID2 expression." (PMID 38961353, 2024). "Mechanistically, we show that in tumor cells the ANGPTL2‐α5β1 integrin pathway promotes PRC2‐mediated H3K27me3 deposition at promoters of antigen presentation‐related genes, including MHC‐I, via JARID2 induction." (PMID 37452654, 2023). "The ANGPTL2–α5β1‐integrin pathway in tumor cells accelerates polycomb repressive complex 2‐mediated repressive histone modification at the major histocompatibility complex class I (MHC‐I) promoter via JARID2 induction, thereby attenuating interferon γ‐induced MHC‐I expression in tumor cells." (PMID 37452654, 2023). "In the TCGA-HCC dataset, 13 genes were identified with significant correlation with SAMD13 from the tumor group only and a total of six genes including FOXM1, JUN, JARID2, BRE, BUB1B, and PHC2 were shown to significantly predict poor overall survival in log-rank tests in HCC." (PMID 37968735, 2023). "In our study, based on the ceRNA hypothesis, tumor-promoting genes, including KCNQ1OT1, JARID2, CDK6, DNMT3A, and TET1, competitively bound the tumor suppressor gene hsa-29c-3p." (PMID 32127798, 2020).
tumor (continued). "Analysis of a dataset of the International Cancer Genome Consortium (ICGC)/The Cancer Genome Atlas (TGCA) pan‐cancer whole genome analysis (n = 1210 samples, 23 tumor types) revealed a negative correlation of JARID2 mRNA levels with those of HLA‐A and HLA‐C mRNAs." (PMID 37452654, 2023). "Expression levels of NEAT1 and GAS5 were also significantly increased in tumor samples compared with adjacent normal tissue (p-value = 2.16e−8 for GAS5 and p-value = 0.01 for NEAT1, t-test), suggesting that they inhibit apoptosis in HCC, perhaps by interacting with EZH2 and JARID2." (PMID 36578923, 2022).
cancer (26 papers, 2010 to 2025). A tumor composed of atypical neoplastic, often pleomorphic cells that invade other tissues. "EZH2 is known to be highly expressed in many cancers, and elevated levels of JARID2 have been implicated in several cancers as well." (PMID 30119689, 2018). "Jarid2 is implicated in signaling pathways regulating cancer cell epithelial-mesenchymal transition, and stem cell maintenance." (PMID 28445934, 2017). "The RNAs bound by EZH2/JARID2 were also closely associated with cancer pathways in HepG2 cells." (PMID 36578923, 2022). "Of the 3 genes included in the panel of epigenetic regulators, DNMT3B (DNA methyltransferase 3 beta) and JARID2 (Jumonji and AT-rich interaction domain containing 2) were overexpressed in iPSCs compared to MSCs and cancer cell lines." (PMID 39621192, 2025). "Our research has initially observed upregulation of JARID2 in OSCC and has begun to investigate its association with enhanced cancer cell proliferation, invasion, and migration." (PMID 38961353, 2024). "Integrating analysis of the RNA and DNA binding profiles suggests EZH2 and JARID2 shift their binding ability from DNA to RNA in HepG2 cells to promote cancer development in HCC." (PMID 36578923, 2022). "It is also reported that EZH2 and JARID2 regulate gene transcription by interacting with lncRNAs in ESCs and cancers." (PMID 36578923, 2022). "Studies have shown that JARID2 was highly expressed in a variety of cancers, and played a role in promoting cancer." (PMID 36471281, 2022). "Except for the its function in the embryological context, JARID2 was also dysregulated in cancer and considered as an oncogene that promotes cancer progression." (PMID 36050314, 2022). "Although JARID2 has also been implicated in the malignant transformation of cancer cells, its role in GBM and its association with cancer stem cells remain unclear." (PMID 40288646, 2025). "ALK expression was associated with methylation of regions/probes harboring repressive histone marks as indicated by the enrichment of chromatin regulators of the PRC2 complex (EZH2, SUZ12, and JARID2), which has been described as “epigenetic switching” in cancer." (PMID 38585847, 2024). "JARID2, as a cancer-promoting gene, is highly expressed in various cancer cells." (PMID 38203196, 2023). "Moreover, we confirmed the effects of JARID2 knockdown in the regulation of the EMT-related genes in another cancer cell line, HT29." (PMID 25542019, 2014). "We then proved that compared to normal oral epithelial cell lines and adjacent normal samples from OSCC patients, JARID2 expression is elevated in OSCC cell lines and cancer tissues." (PMID 38961353, 2024). "Another study also found that the sponge function of linc00649 led to a low expression level of the cancer suppressor gene miR-16-5p in BLCA cell lines, thus enhancing transcription of the miR-16-5p target gene Jumonji AT-rich interactive domain 2 (JARID2)." (PMID 36831352, 2023). "The most prevalent altered cancer-related genes were CTNNB1 (16%) and ZNRF3 (16%), followed by EGFR (11%), JARID2 (11%), KMT2B (11%), KMT2C (11%), NSD1 (11%), PIK3CA (11%), SH2B3 (11%), and UBR5 (11%)." (PMID 38023213, 2023). "Uncovering how JARID2 and SFRP1 modulate cancer progress and patient survival in these cancers will be an important future direction of this study." (PMID 30119689, 2018). "Altogether, these results indicated that knockdown of JARID2 counteracted TGF-ß-induced morphological changes and cytoskeletal rearrangements of A549 and HT29 cancer cells characteristic of EMT." (PMID 25542019, 2014). "Jarid2 is a co-factor of PRC2, a multi-component histone methyltransferase (HMT) complex with important functions in differentiation and cancer." (PMID 23185331, 2012).
cancer (continued). "Quantitative gene transcript analysis at early time points (from 30 min to 24 h) showed statistically significant induction of various histone demethylases such as JARID1A, JARID2, JMJD1A, and KDM6A/B in all the three cancer cell types grown in detached conditions." (PMID 35186918, 2022). "In addition, we found that EED, a core component of PRC2, and JARID2, an accessary factor of PRC2, were essential for TGF-β-induced EMT through CDH1 repression in cancer cells." (PMID 33779563, 2021). "Future studies are still needed in order to identify whether PALI1 (and JARID2) are methylated in cis or by another PRC2 complex and if the degree of methylation changes during normal development or in cancer and other pathologies." (PMID 34321472, 2021). "Finally, we show that JARID2 and SFRP1 are negatively correlated in cancer and correlate with overall survival and life span, suggesting that the repression of SFRP1 by JARID2 has important implications outside of skeletal muscle as well." (PMID 30119689, 2018). "Moreover, we also examined the effects of JARID2 knockdown in the status of histone H3 methylation and EZH2 recruitment on the regulatory regions of CDH1 and miR-200 family genes in another cancer cell line, HT29." (PMID 25542019, 2014). "Interestingly, ANGPTL2 mRNA levels show a significant positive correlation with those of JARID2 mRNA, and levels of both are negatively correlated with those of HLA‐B and HLA‐C mRNAs in cancer lines derived from metastatic rather than primary lesions." (PMID 37452654, 2023). "In summary, we demonstrated that EZH2/JARID2 has a significant and specific preference to bind to the highly expressed and cancer-related genes in the HepG2 cell line, which may partially explain the contribution of EZH2/JARID2 in the carcinogenesis and progression of HCC." (PMID 36578923, 2022). "Therefore these results together suggested that JARID2 was required for TGF-ß-dependent changes of histone H3 methylation and EZH2 recruitment on the specific target genes during TGF-ß-induced EMT process of A549 and HT29 cancer cell lines." (PMID 25542019, 2014). "However, the role of JARID2, an interacting component of PRC2, during cancer progression remains unknown." (PMID 25542019, 2014). "Therefore, it is not difficult to understand that JARID2-mediated suppression of PTEN can activate downstream AKT signaling, and enhance cancer cell invasion ability by inducing EMT in HCC cells." (PMID 27259236, 2016).
infection (5 papers, 2019 to 2026). The state of being infected such as from the introduction of a foreign agent such as serum, vaccine, antigenic substance or organism. "If anything, Jarid2-deficient cells tended to undergo terminal differentiation faster than controls, based on the increased frequency of TE cells on day 5 post-infection." (PMID 31089138, 2019). "It was reported that REV-T upregulates gga-miR-155 expression in CEF cells after infection, while gga-miR-155 promotes cell survival by targeting jumonji and AT-rich interaction domain containing 2 (JARID2), a cell cycle regulator, and facilitates viral replication." (PMID 31683847, 2019).